TNF (tumor necrosis factor)
Diseases named in the same sentence as TNF in open-access papers (continued):
Sharing a sentence is not in itself a finding about the gene and the disease.
inflammatory bowel disease (continued). "A LOR to anti-TNF agents―and, consequently, DI―occurs frequently in inflammatory bowel disease, with an overall rate of DI requirement of approximately one-fourth at one year and one-third at three years." (PMID 34069295, 2021). "Adalimumab (ADA) is a human anti-tumor necrosis factor (TNF-α) monoclonal antibody used in inflammatory bowel diseases, such as Crohn’s disease (CD)." (PMID 34959633, 2021). "We evaluated the relationship between patient sex and serum TNF antagonist drug and antibody concentrations in inflammatory bowel disease." (PMID 35004778, 2021). "For example, MMP-13 can promote inflammatory bowel disease in mice through cleavage of pro- tumor necrosis factor (TNF)-α to generate its mature form." (PMID 33671187, 2021). "The study by Narayanan and colleagues showed that exogenous treatment with irisin, given i.p. at 18 ng/mL twice a week for 3 weeks, reduced the expression of tumor necrosis factor-alpha (TNF-α) in rats with inflammatory bowel disease." (PMID 34639200, 2021). "While anti-tumor necrosis factor alpha (TNF-α) therapy has been proven effective in inflammatory bowel disease (IBD), approximately 40% of patients lose the response." (PMID 34556023, 2021). "Since anti-TNF agents are often used to treat gastrointestinal inflammatory disease, it is puzzling that inflammatory bowel disease developed in this setting." (PMID 35095905, 2021). "In contrast, tumor necrosis factor α (TNFα), a key mediator of different inflammatory disorders, including inflammatory bowel disease (IBD), can inhibit Hep expression, and treatment with anti-TNFα antibodies improved anemia status in patients with IBD." (PMID 33918997, 2021). "The used search terms were ‘inflammatory bowel disease’, ‘tumor necrosis factor’, ‘Crohn’, ‘ulcerative colitis’, ‘TNF’, ‘adalimumab’, ‘certolizumab’, ‘infliximab’, ‘natalizumab’, ‘ustekinumab’, and ‘vedolizumab’." (PMID 33802483, 2021). "TNF signaling pathways and inflammatory bowel disease (IBD) are closely related to the inflammatory reaction process." (PMID 34221084, 2021). "The development of biomarkers to guide management of anti–tumor necrosis factor (TNF) agents in patients with inflammatory bowel disease (IBD) is an unmet need." (PMID 33735154, 2021). "Infliximab is a monoclonal IgG1 antibody that binds specifically to TNF-α and is a TNF-α inhibitor that has been successfully used in the management of inflammatory bowel disease." (PMID 33927720, 2021). "In cases of inflammatory bowel disease induced by dextran sodium sulfate, F. dibotrys can down-regulate tumor necrosis factor-α (TNF-α), as well interleukin (IL)-6, IL-1β and IL-10." (PMID 34530893, 2021). "One patient developed features of inflammatory bowel disease, 5 years after initiation of anti-TNF therapy." (PMID 35095905, 2021). "Future studies are needed to assess the effect of patient sex, i.e., sex hormones, on anti-TNF anti-drug antibody and serum drug concentrations in patients with inflammatory bowel disease." (PMID 35004778, 2021). "Infliximab (IFX) is a chimeric IgG1 monoclonal antibody against tumor necrosis factor alpha (TNFα) used in a wide range of inflammatory diseases, such as inflammatory bowel disease and spondyloarthropathies." (PMID 34452152, 2021). "Antibodies developed to block TNF have revolutionised the treatment of inflammatory bowel diseases, Crohn’s disease and ulcerative colitis." (PMID 33657181, 2021). "In the case of murine models of inflammatory bowel disease, TNF-α production was attenuated by the activation of the FXR receptor, in which CDCA is a potent agonist." (PMID 34452145, 2021). "Of note, a retrospective cohort study of a population diagnosed with inflammatory bowel disease (IBD) revealed a higher incidence of PD among IBD patients compared to healthy subjects, and exposure of these patients to anti-TNF-α therapy was associated with reduced PD incidence." (PMID 33854417, 2021).
inflammatory bowel disease (continued). "Current studies have shown that anti-TNF drugs can be used to exert anti-inflammatory effects, thereby effectively treating inflammatory bowel disease; however, few studies have proven that drugs act directly through TNF signaling pathways." (PMID 34671661, 2021). "In most inflammatory bowel diseases, IL-1β acts together with other proinflammatory cytokines such as IL-6 and tumor necrosis factor-α or IL-23 in the inflammatory process, and treatment alone against the proinflammatory effects of IL-1β has little effect." (PMID 33553436, 2021). "Polyphenols reduce inflammation by suppressing the pro-inflammatory cytokines in inflammatory bowel disease by inducing Treg cells in the intestine, inhibition of tumor necrosis factor-alpha (TNF-α) and induction of apoptosis, decreasing DNA damage." (PMID 33668814, 2021). "The increased abundance of [Eubacterium] _rectale_group in patients with inflammatory bowel disease indicates anti-TNF-α enhancement." (PMID 33790981, 2021). "As already discussed, systemic TNF neutralization is a standard treatment for such autoimmune diseases as rheumatoid arthritis, psoriasis, and inflammatory bowel disease (IBD)." (PMID 33917839, 2021). "The expression of Triggering Receptor Expressed on Myeloid cells (TREM)-1 has been described as a predictive marker for anti-Tumor Necrosis Factor (TNF)-α monoclonal antibody (mAb) therapy responsiveness in patients with inflammatory bowel disease (IBD)." (PMID 33790898, 2021). "Anti-tumor necrosis factor (TNF) therapy has greatly improved the medical treatment of inflammatory bowel diseases, and infliximab was the first approved anti-TNF agent." (PMID 34354708, 2021). "In vascular endothelial cells, inflammatory bowel disease, T cells and fibroblasts, TNF-α is anti-inflammatory and TGF-β is pro-inflammatory." (PMID 35069596, 2021). "The TNF-α plays a crucial roles in the pathophysiology of inflammatory bowel disease and has the ability to negatively affect the mucosal immune system and causing colonic damage." (PMID 34310635, 2021). "Infliximab, which is a monoclonal antibody to tumor necrosis factor alpha (TNFα), has become the mainstay therapeutic agent for treating moderate to severe pediatric inflammatory bowel disease (PIBD)." (PMID 33520903, 2020). "In patients with inflammatory bowel disease, a large population of inflammatory cells infiltrated in the mucosa, excessive inflammatory cytokines including tumor necrosis factor (TNF)-α, interleukin (IL)-18, IL-6, IL-1β were secreted." (PMID 33240089, 2020). "Current recommendations counterindicate the use of TNFα-blockers in patients with inflammatory bowel disease who had a cancer diagnosis in the last 5 years." (PMID 32391269, 2020). "The introduction of anti‐tumor necrosis factor alpha (anti‐TNF) medications, including infliximab and adalimumab, has revolutionized the management of patients with inflammatory bowel disease (IBD)." (PMID 32514462, 2020). "The use of anti-tumor necrosis factor (anti-TNF) agents has revolutionized the treatment of inflammatory bowel diseases (IBDs), which include Crohn’s disease (CD)." (PMID 32922288, 2020). "It plays a major role in many chronic inflammatory diseases, including RA and inflammatory bowel disease, as evidenced by experimental overexpression of TNF in different rodent models as well as by targeted TNF blockade in patients." (PMID 32662821, 2020). "Experiments with the knock-in mice with a deletion that results in TNF overproduction, showed the development of chronic inflammatory arthritis and inflammatory bowel disease." (PMID 32967383, 2020). "In a slightly different model, overexpression of mouse TNF by deletion of the adenylate-uridylate–rich elements in the murine TNF locus (TNFΔARE mice) induces not only destructive polysynovitis, including sacroiliitis, but also inflammatory bowel disease." (PMID 32662821, 2020).
inflammatory bowel disease (continued). "By targeting various host immune molecules such as tumor necrosis factor (TNF), interleukins and adhesion molecules present on the surfaces of lymphocytes, biologics agents have revolutionized the medical management of inflammatory bowel disease (IBD)." (PMID 32138717, 2020). "Anti‐Tumor Necrosis Factor (TNF)‐induced lupus (ATIL) is a distinct clinical entity, increasingly recognized in patients with inflammatory bowel disease treated with anti‐TNF therapy." (PMID 32514462, 2020). "Previous reports have shown that the inhibition of soluble TNF signaling in a murine model of inflammatory bowel disease has little therapeutic effect; however, the inhibition of transmembrane TNF results in remission." (PMID 33585287, 2020). "Soteria® and PhloralTM platform technologies are currently being investigated for sustained release colon tissue delivery of anti-TNF-α mAbs to provide a novel oral treatment for chronic inflammatory diseases such as inflammatory bowel disease (IBD)." (PMID 33096803, 2020). "Treatment options for inflammatory bowel disease (IBD) radically changed after the introduction of monoclonal antibodies to tumour necrosis factor alpha (TNF-α)." (PMID 32813123, 2020). "Paradoxical inflammation occurred involving the skin, joints and lungs under anti-TNF treatment in patients with inflammatory bowel disease." (PMID 33193322, 2020). "In animal models of inflammatory skin disease, NPI 32,101 was shown to decrease inflammation and down-regulates the production of interleukin-12 (IL-12), tumor necrosis factor-alpha (TNF-α) involved in the pathogenesis of inflammatory bowel disease." (PMID 32751448, 2020). "Previous studies on inflammatory bowel disease have shown that UDCA specifically inhibits TNFα-induced IL-8 release from monocytes by inhibiting TNF receptor associated factor (TRAF2) activation." (PMID 33129276, 2020). "For example, one recent study found that CSO treatment protected against inflammatory bowel disease (IBD) by reducing the expression of inflammatory cytokines such as TNF-α, IL-1β, IL-6, and IL-17." (PMID 32917229, 2020). "Infliximab (IFX), a TNF-α blocking chimeric monoclonal antibody, induces clinical response and mucosal healing in patients with inflammatory bowel disease (IBD)." (PMID 32933548, 2020). "Monoclonal antibodies targeting TNF-a, including infliximab (Remicade), adalimumab (Humira), and certolizumab pegol, have all been shown to be effective in inflammatory bowel diseases." (PMID 32486412, 2020). "Many cytokines such as TNF-α, IL-6, and IL-1β play a key role in the pathogenicity of inflammatory bowel disease, in regulating inflammation of the intestinal mucosa, and in the integrity of the intestinal epithelium." (PMID 33204254, 2020). "These DEPs were enriched in inflammatory bowel disease, antigen processing and presentation, Th17 cell differentiation, toll-like receptor signaling pathway, TNF signaling pathway, and other signaling pathways related to the immune response." (PMID 32799626, 2020). "Rationale: Anti-tumor necrosis factor (TNF) therapy is a very effective way to treat inflammatory bowel disease." (PMID 32929381, 2020). "The advent of anti-TNF agents as the first approved targeted therapy in the treatment of inflammatory bowel disease (IBD) patients has made a major impact on our existing therapeutic algorithms." (PMID 32984386, 2020). "Anti-Tumor Necrosis Factor-alpha therapy has become clinically important for treating inflammatory bowel disease." (PMID 31238939, 2019). "We previously demonstrated in rats with inflammatory bowel disease decreased osteocyte density and increased apoptosis concurrent with elevated osteocyte TNF-α." (PMID 31139147, 2019). "For future studies, cohorts with other TNF-driven conditions such as e.g., inflammatory bowel diseases should be added as disease controls." (PMID 31338093, 2019).
inflammatory bowel disease (continued). "Phe has been reported to possess protective effects in the treatment of inflammatory bowel disease via inhibiting tumor necrosis factor-α (TNF-α) productions while enhancing immune responses." (PMID 30691236, 2019). "TNF-α is a potent pro-inflammatory cytokine thought to be involved in the pathogenesis of inflammatory bowel disease and has been reported to promote inflammation and colitis-associated cancer." (PMID 30883594, 2019). "In literature, we have only found one single case of VL in a patient with inflammatory bowel disease (Crohn’s disease) on TNF-α antagonists." (PMID 31463070, 2019). "Infliximab is an anti-TNF-α inhibitor that has been well-studied in treating inflammatory bowel disease." (PMID 30777137, 2019). "In the last two decades anti‐tumor necrosis factor (anti‐TNF) therapy for inflammatory bowel disease (IBD) has been widely used to induce and maintain clinical and endoscopical remission, completely changing management of the disease." (PMID 31322753, 2019). "A fundamental role of TNF-α in NIM-CMPA has previously been indicated, as high concentrations of fecal TNF-α have been reported in children with inflammatory bowel disease and CMPA patients manifesting intestinal symptoms." (PMID 31428100, 2019). "Various studies showed that IL-1, IL-6, and TNF-α play a key role in invoking inflammatory cells and tissue damage in inflammatory bowel diseases." (PMID 31143692, 2019). "In support of our findings, anti-TNF drugs have been previously reported to inhibit the classical complement pathway in inflammatory bowel disease, and to decrease serum levels of C3 and C4 in PsA and RA." (PMID 31335881, 2019). "Tumor necrosis factor (TNF)-α antagonism ameliorates ischemia/reperfusion injury and hydrogels delivering anti-TNF-α have been used for several applications such as burns, wound healing or inflammatory bowel disease (IBD)." (PMID 30949485, 2019). "Tumor necrosis factor-α inhibitors represent a contemporary targeted therapy for a spectrum of autoimmunity-mediated disorders such as rheumatoid arthritis and inflammatory bowel disease." (PMID 30836705, 2019). "Garlic has been found to increase IL-10 and inhibit TNF-α and IL-6 production in placental cell culture, and TNF-α in inflammatory bowel disease." (PMID 30619868, 2018). "Dysregulation of TNF-α production and distribution has been demonstrated in various human diseases, including cancers, dermatoses, and inflammatory bowel diseases." (PMID 30518097, 2018). "The transcriptional factor NF-κB is known to regulate the level of TNF-α, IL-6, and IL-1β during the progression of inflammatory bowel disease." (PMID 29483924, 2018). "Pentoxifylline, a medicine used for improving the circulation, has been reported to inhibit TNF-α production and to ameliorate inflammatory bowel disease and non-alcoholic steatohepatitis." (PMID 30338039, 2018). "Tumor necrosis factor-alpha (TNFα), a critical co-factor for mucosal Th1 cytokine production, plays a central role in the pathogenesis of mucosal inflammation in inflammatory bowel disease." (PMID 30305177, 2018). "The so-called “biologicals” (monoclonal antibodies to various inflammatory targets like tumor necrosis factor or integrins) have revolutionized the treatment of inflammatory bowel diseases." (PMID 30135722, 2018). "Use of appropriate alternatives and controls is particularly important for models of diseases where anti‐TNF‐α therapies are used clinically, such as rheumatological and inflammatory bowel diseases." (PMID 27669117, 2017). "One third of patients with inflammatory bowel disease (IBD) inadequately respond to anti-TNF treatment and preclinical data suggest that matrix metalloproteinase-9 (MMP-9) is a novel therapeutic target." (PMID 28561062, 2017). "More recently, anti-TNF therapy has been shown to be effective in inflammatory bowel disease in part through suppressing IL-22-binding protein thereby implicating IL-22 as a protective cytokine." (PMID 29163483, 2017).
inflammatory bowel disease (continued). "Prospective study of infants born to mothers with inflammatory bowel disease treated throughout pregnancy with anti-TNF-α (adalimumab/infliximab)." (PMID 28983301, 2017). "The use of biologic agents, particularly anti-tumor necrosis factor (TNF)-α, has revolutionized the treatment of inflammatory bowel diseases (IBD), modifying their natural history." (PMID 28906475, 2017). "In the pathogenesis of inflammatory bowel disease, the secretion of the proinflammatory cytokine plays an important role, especially TNF-α." (PMID 28798800, 2017). "Two of them had been already on TNF-α inhibitors for pre-existing inflammatory bowel disease, when diagnosed with childhood TAK." (PMID 29166923, 2017). "In a mouse model of inflammatory bowel disease, peritoneal M2 macrophages induced by T. spiralis suppressed the production of pro-inflammatory cytokines such as TNF-α and IL-6, and consequently reduced the severity of inflammation." (PMID 28542159, 2017). "TNFα is mainly secreted by primitive neutrophils and participates in the inflammatory response involved in rheumatoid arthritis and inflammatory bowel disease." (PMID 29201923, 2017). "The introduction of anti-tumor necrosis factor (TNF) agents has greatly changed the treatment paradigm of patients with inflammatory bowel disease (IBD), including CD." (PMID 28542298, 2017). "There is an exacerbation of TNFα expression along with other inflammatory mediators in the intestinal lamina propria of the inflammatory bowel diseases (IBD)." (PMID 28487813, 2017). "TNFα release is connected with inflammation and pain related sensation in patients with inflammatory diseases like hepatitis, inflammatory bowel disease, pancreatitis, and neuropathic complications." (PMID 28587181, 2017). "TNFα AU-rich elements (AREs) are targets for p38 and JNK kinase signaling, and deletion of TNFα AREs leads to the overexpression of TNFα, further exacerbating chronic inflammatory arthritis and inflammatory bowel disease." (PMID 29201923, 2017). "Activation of the TNF-α receptor (TNFR) leads to an inflammatory response, and anti-TNF therapy has been administered to reduce inflammation symptoms and heal mucosal ulcers in inflammatory bowel disease (IBD)." (PMID 29176974, 2017). "At the same time, Wip1 knockout mice exhibit pro-inflammatory phenotype in skin and intestine in the model of inflammatory bowel disease (IBD) with elevated levels of inflammation-promoting cytokines TNF-α, IL-6, IL-12, IL-17." (PMID 28417018, 2017). "In inflammatory bowel disease (IBD) patients, TNF-α is a crucial player that causes the loss of intestinal epithelial barrier integrity and stimulates the release of other proinflammatory cytokines." (PMID 28607532, 2017). "More recently, Li and colleagues also confirmed these low numbers of pre-switched memory B cells in inflammatory bowel disease and its restoration with TNFα-blockers." (PMID 27468085, 2016). "Association between single-nucleotide polymorphisms SNPs and response to anti-tumor necrosis factor (TNF) drugs (infliximab and/or adalimumab) in patients with inflammatory bowel disease." (PMID 26861312, 2016). "Tumor necrosis factor-alpha (TNF-α) is known to be one of the key cytokines for granuloma formation in both sarcoidosis and inflammatory bowel diseases." (PMID 26864464, 2016). "Monocytes are the principal source of TNF-α in humans and are believed to be central in many diseases, including inflammatory bowel disease, arthropathies, and septic shock." (PMID 27747245, 2016). "Inflammatory bowel disease was induced by the over-expression of pro-inflammatory cytokines (TNF-α, IL-1, IL-6, and IL-12) and/or the down-regulation of anti-inflammatory cytokines in the polarization of Th1/Th2 cells in colonic mucosa." (PMID 27932984, 2016). "Anti-TNF-α molecules, which block both soluble and membrane bound TNF-α, are effective in inflammatory arthropathies and inflammatory bowel disease." (PMID 27747245, 2016).